SNORA68B (small nucleolar RNA, H/ACA box 68B)
Gene: Small nucleolar RNA gene on chromosome 19 (32,608,337 to 32,608,469, reverse strand). Ensembl gene ENSG00000201388.
Gene Ontology:
Biological process: RNA processing
Cellular component: nucleolus
Homologues: Orthologues: chimpanzee SNORA68B (98% identical), macaque SNORA68B (92% identical). Paralogues in human: SNORA68 (89% identical).